MAP4K2 (mitogen-activated protein kinase kinase kinase kinase 2)
Description:
Serine/threonine-protein kinase which acts as an essential component of the MAP kinase signal transduction pathway. Acts as a MAPK kinase kinase kinase (MAP4K) and is an upstream activator of the stress-activated protein kinase/c-Jun N-terminal kinase (SAP/JNK) signaling pathway and to a lesser extent of the p38 MAPKs signaling pathway. Required for the efficient activation of JNKs by TRAF6-dependent stimuli, including pathogen-associated molecular patterns (PAMPs) such as polyinosine-polycytidine (poly(IC)), lipopolysaccharides (LPS), lipid A, peptidoglycan (PGN), or bacterial flagellin. To a lesser degree, IL-1 and engagement of CD40 also stimulate MAP4K2-mediated JNKs activation. The requirement for MAP4K2/GCK is most pronounced for LPS signaling, and extends to LPS stimulation of c-Jun phosphorylation and induction of IL-8. Enhances MAP3K1 oligomerization, which may relieve N-terminal mediated MAP3K1 autoinhibition and lead to activation following autophosphorylation. Also mediates the SAP/JNK signaling pathway and the p38 MAPKs signaling pathway through activation of the MAP3Ks MAP3K10/MLK2 and MAP3K11/MLK3. May play a role in the regulation of vesicle targeting or fusion. regulation of vesicle targeting or fusion. Activator of the Hippo signaling pathway which plays a pivotal role in organ size control and tumor suppression by restricting proliferation and promoting apoptosis. MAP4Ks act in parallel to and are partially redundant with STK3/MST2 and STK4/MST2 in the phosphorylation and activation of LATS1/2, and establish MAP4Ks as components of the expanded Hippo pathway.
Synonyms: GCK; RAB8IP; BL44
Tractability: Small molecule: a high-quality ligand is known; it belongs to a druggable protein family. Antibody: UniProt places it where antibodies can reach, with medium confidence; its Gene Ontology location is reachable by antibodies, with medium confidence. PROTAC: it is named in the literature on targeted protein degradation; UniProt records ubiquitination sites on it; ubiquitination databases record sites on it; its protein half-life has been measured; a small molecule that binds it is known.
Target class: Protein Kinase; STE protein kinase STE20 family; STE protein kinase group; Enzyme; Kinase; STE protein kinase KHS subfamily
Chemical probes: NG25 (high quality), TL4-12 (high quality)
Safety:
Unwanted effects reported when the protein is acted on. In parentheses: how it was acted on, where the effect was seen, and who reports it.
cardiac arrhythmia (cardiovascular system; source: Lamore et al. (2017))
Gene: Protein-coding gene on chromosome 11 (64,784,918 to 64,803,241, reverse strand). Ensembl gene ENSG00000168067.
Subcellular location: Cytoplasm; Basolateral cell membrane; Golgi apparatus membrane
Subcellular location (Human Protein Atlas): Vesicles
Gene Ontology:
Molecular function: ATP binding; mitogen-activated protein kinase kinase kinase binding; protein binding; protein serine kinase activity; protein serine/threonine kinase activity; MAP kinase kinase kinase kinase activity; protein kinase activity
Biological process: intracellular signal transduction; positive regulation of JNK cascade; protein phosphorylation; immune response; JNK cascade; vesicle-mediated transport
Cellular component: cytoplasm; Golgi membrane; basolateral plasma membrane
Genetic constraint (gnomAD): Loss-of-function variants: 85 observed, 117.48 expected, observed/expected ratio (o/e) 0.72, 90% interval 0.61 to 0.87. The upper end of that interval is the gene's LOEUF score, 0.87, which puts it in group 3 of 6, group 1 being the genes least tolerant of losing a copy. Missense variants: 923 observed, 1,020.9 expected, observed/expected ratio (o/e) 0.9, 90% interval 0.86 to 0.95. Synonymous variants: 479 observed, 417.56 expected, observed/expected ratio (o/e) 1.15, 90% interval 1.06 to 1.24.
Homologues: Orthologues: macaque MAP4K2 (98% identical), pig MAP4K2 (95% identical), chimpanzee MAP4K2 (95% identical), dog MAP4K2 (95% identical), guinea pig MAP4K2 (94% identical), mouse Map4k2 (94% identical), rat Map4k2 (91% identical). Paralogues in human: MAP4K3 (57% identical), MAP4K5 (53% identical), MAP4K1 (43% identical), MINK1 (28% identical), MAP4K4 (28% identical), TNIK (28% identical), SLK (23% identical), NRK (23% identical), STK10 (22% identical), TAOK1 (21% identical), TAOK3 (20% identical), TAOK2 (19% identical), and 23 more.
Diseases named in the same sentence as MAP4K2 in open-access papers:
MAP4K2 is named in the same sentence as 22 diseases in open-access papers, as found by Europe PMC text mining. Sharing a sentence is not in itself a finding about the gene and the disease. The quoted sentences say what the papers report.
colorectal cancer (3 papers, 2012 to 2024). A primary or metastatic malignant neoplasm that affects the colon or rectum. "A recent study showed that inhibiting MAP4K2 with BAY61-3606 can sensitize KRAS wild-type colorectal cancer cells to AZ628, a RAF kinase inhibitor, suggesting a potential therapeutic strategy for treating colorectal cancer." (PMID 38111008, 2023). "From these data, we conclude that MAP4K2 functions upstream in the NFκβ pathway to regulate the response of colorectal cancer cells to inhibition of RAF." (PMID 22815993, 2012).
Anxiety (1 paper, 2022). Intense feelings of nervousness, tension, or panic often arise in response to interpersonal stresses. "Additionally, Map4k2, also upregulated here and identified as a transcriptomic signature, has some links to anxiety associated with early life stress." (PMID 36364936, 2022).
asthma (1 paper, 2023). "Furthermore, the gene present in both models was MAP4K2; this gene family has been extensively associated with airway inflammation in asthma and COPD, including experimental demonstrations that it can be induced by cigarette smoke exposure." (PMID 37175432, 2023).
gout (1 paper, 2018). A condition characterized by painful swelling of the joints, which is caused by deposition of urate crystals. "The SNPs rs55975541 in CDC42BPG, and rs11231825/rs9734313 in SLC22A12/NRXN2, and rs10897526 in MAP4K2 on chromosome 4 were previously reported to be associated with hyperuricemia or gout." (PMID 29558500, 2018).
head and neck squamous cell carcinoma (1 paper, 2023). A squamous cell carcinoma that arises from any of the following anatomic sites: lip and oral cavity, nasal cavity, paranasal sinuses, pharynx, larynx, and salivary glands. "In the context of head and neck squamous cell carcinoma (HNSCC), although MAP4K2 is not considered part of the STRIPAK complex, its close association with the complex members is crucial to maintaining tissue homeostasis in HNSCC, via regulation of YAP/TAZ." (PMID 38201504, 2023).
Hyperglycemia (1 paper, 2022). An increased concentration of glucose in the blood. "qRT-PCR assays indicated the expression of cMAP4K2 but not MAP4K2 mRNA was significantly induced in the hyperglycemia group (25 mM of D-glucose) compared with the normoglycemia group (5 mM glucose) or L-glucose group." (PMID 35963645, 2022).
liver cancer (1 paper, 2022). An epithelial or non-epithelial malignant neoplasm that arises from the liver. "MAP4K2 is known as an unfavourable prognostic marker of liver cancer." (PMID 36582804, 2022).
melanoma (1 paper, 2012). A malignant, usually aggressive tumor composed of atypical, neoplastic melanocytes. "Moreover, MAP4K2 has been shown to positively regulate NFκβ to protect melanoma cells from UV-induced apoptosis." (PMID 22815993, 2012).
metastatic disease (1 paper, 2012).
ovarian carcinoma (1 paper, 2024). A malignant neoplasm originating from the surface ovarian epithelium. "Furthermore, FCGBP, MAP4K2, IL12A, and HSPA2 showed similar expression levels in ovarian cancer compared to normal tissues." (PMID 39149564, 2024).
pancreatic cancer (1 paper, 2026). "Remarkably, the anti-PD-1 immunotherapeutic effect on pancreatic cancer was significantly improved in T-Map4k2 cKO mice, Treg-specific Map4k2-deficient mice, adoptively transferred chimeric mice, or MAP4K2-inhibitor-treated mice." (PMID 41615953, 2026). "Consistently, scRNA-seq analysis of patients with pancreatic cancer showed increased MAP4K2 levels in infiltrating Treg cells." (PMID 41615953, 2026).
Sepsis (1 paper, 2023). Sepsis is defined as life-threatening organ dysfunction caused by a dysregulated host response to infection. "Furthermore, we observed that in both baboon sepsis models, 3 other miR-93-5p targets, ZAP70, MAP3K3, and MAP4K2, were downregulated after induction of sepsis." (PMID 37261908, 2023).
tumor (5 papers, 2012 to 2025). "HG6-64-1, a chemical inhibitor of MAP4K2, significantly suppresses tumor growth and prolongs survival in mouse models." (PMID 41034525, 2025). "The inhibition of MAP4K2 led to a significant reduction in tumor growth, underscoring its critical role in tumorigenesis." (PMID 41034525, 2025). "Treatment with TL4-12 significantly reduced tumor size and weight in these models, highlighting the promise of MAP4K2 inhibitors as potential therapeutic agents for HNC32." (PMID 41034525, 2025). "Preclinical studies have shown that MAP4K2 inhibitors, such as TL4-12, can effectively suppress tumor growth and induce apoptosis in RAS-mutant MM cells." (PMID 41034525, 2025).
infection (2 papers, 2017). The state of being infected such as from the introduction of a foreign agent such as serum, vaccine, antigenic substance or organism. "We provide evidence that treatment of infected cells with a selective chemical inhibitor of MAP4K2, one of the protein kinases found to be activated by infection, severely affects HCV genome replication." (PMID 28480889, 2017). "Our microarray data revealed a major suppression of several components of the JNK pathway (MAP4K2, MAP3K5, MAP2K7 and MAP2K4), with the exception of JNK2 (also known as MAPK9), which was increased at 24 h; the other two Jun kinases, JNK1 and JNK3, were not significantly affected by infection." (PMID 28480889, 2017).
MAP4K2 also shares sentences with these, for which no sentence is quoted: autoimmune disease (2 papers); cancer (2); acute myeloid leukemia (1); atherosclerosis (1); bacterial infection (1); diabetes (1); hyperuricemia (1); leukemia (1).